CDK1 (cyclin dependent kinase 1)
Diseases named in the same sentence as CDK1 in open-access papers (continued):
Sharing a sentence is not in itself a finding about the gene and the disease.
breast cancer (continued). "In order to further understand the role of CDK1 in breast cancer, especially its role in the tumor immune microenvironment, we analyzed the relationship between different immune cell subtypes and CDK1 expression." (PMID 41278293, 2025). "CDK1 acts as a multifaceted oncogenic factor in breast cancer, contributing to tumor growth and immune modulation." (PMID 41278293, 2025). "CDK1 plays a dual role in breast cancer, normally triggering mitosis but, when inhibited by C. urens, halting cell division." (PMID 40081286, 2025). "In this study, we systematically analyzed the expression pattern, clinical relevance, and functional implications of CDK1 in breast cancer." (PMID 41278293, 2025). "We found that the high expression of CDK1 in the breast cancer cell line (MCF-7) was different from that in the normal breast epithelial cell line (MDA-MB-231), suggesting its potentially important role in breast cancer." (PMID 41278293, 2025). "The study focuses on exploring the therapeutic potential of Caryota urens fruit against breast cancer, specifically targeting cell cycle genes CDK1, CDC25A, and PLK1 through bioinformatics, network pharmacology, and in vitro validation." (PMID 40081286, 2025). "The concurrent demonstration of both computational binding and functional downregulation strongly supports CDK1 as a potential binding site of PAB in canine mammary tumor cells." (PMID 41142571, 2025). "The expression of CDK1 also showed obvious distribution differences in different PAM50 breast cancer subtypes." (PMID 41278293, 2025). "Mechanistically, CD2BP2‐DT drives YBX1 phase separation to stabilize CDK1 and promote breast cancer progression." (PMID 39976088, 2025). "Our data demonstrated that CDK1 is upregulated in tumor tissues compared with normal breast tissues, both in TCGA datasets and breast cancer cell lines." (PMID 41278293, 2025). "CD2BP2‐DT mediates the phase separation of YBX1, thereby stabilizing CDK1 mRNA and promoting the proliferation of breast cancer cells." (PMID 39976088, 2025). "Conversely, NFIX inhibits breast cancer cell proliferation by delaying mitotic entry via CDK1 suppression." (PMID 40746552, 2025). "CDK1 expression was elevated in breast cancer tissues compared with normal controls and exhibited high diagnostic accuracy (AUC = 0.978)." (PMID 41278293, 2025). "Elevated CDK1 levels were associated with HER2-, ER-, and PR-negative subtypes and enriched in Basal-like breast cancer." (PMID 41278293, 2025). "This study aimed to comprehensively evaluate CDK1 expression, prognostic value, and biological functions in breast cancer through integrated bioinformatics and experimental analyses." (PMID 41278293, 2025). "In our study, patients with high proportions of CDK1+ cancer cells in metastatic HER2 breast cancer patients who were validated in a neoadjuvant cohort had poor responses to T-DM1." (PMID 41016944, 2025). "CDK1, essential for G2 to mitosis transition, is frequently overexpressed in breast cancer, promoting uncontrolled proliferation." (PMID 40081286, 2025). "Conversely, CDK1 knockdown effectively attenuated the proliferative effect of CD2BP2‐DT overexpression in breast cancer cells." (PMID 39976088, 2025). "First, we compared the expression levels of CDK1 in normal tissues and tumor tissues by analyzing the RNA-sequencing data (Level 3) for the breast cancer cohort from TCGA." (PMID 41278293, 2025). "The results of the ActD rescue experiment showed that CDK1 mRNA stability was reduced in breast cancer cells following CD2BP2‐DT knockdown, and this reduction was partially reversed by YBX1 overexpression in the context of CD2BP2‐DT knockdown." (PMID 39976088, 2025).
breast cancer (continued). "In parallel, we assessed the functional role of CDK1 in breast cancer cell viability through CDK1 knockdown experiments." (PMID 41278293, 2025). "Further experiments demonstrated that CD2BP2‐DT enhances breast cancer cell proliferation by modulating the expression of CDK1." (PMID 39976088, 2025). "Conversely, CDK1 mRNA stability was increased in breast cancer cells after CD2BP2‐DT overexpression, but this increase was inhibited when YBX1 was knocked down during CD2BP2‐DT overexpression." (PMID 39976088, 2025). "Our results showed that the kinase activity of Cdk1 was regulated by RGC-32 in ER+ breast cancer cells." (PMID 40720499, 2025). "Disrupted expression of core circadian genes (BMAL1, CLOCK and PER3) and hub genes such as ACTB, GAPDH and CDK1 suggests that circadian gene dysregulation promotes breast cancer progression and represents a potential therapeutic target." (PMID 41908013, 2025). "Consistently, CCK-8 assays demonstrated that CDK1 knockdown impaired the proliferative capacity of breast cancer cells." (PMID 41278293, 2025). "In conclusion, CDK1 overexpression is closely associated with malignant progression, poor survival, immune infiltration, and AKT-driven proliferation in breast cancer." (PMID 41278293, 2025). "In conclusion, CD2BP2‐DT promotes the expression of total CDK1 protein and markedly upregulates CDK1Thr161 levels, thereby facilitating the G2/M phase transition in breast cancer cells." (PMID 39976088, 2025). "Our findings indicate that elevated levels of CDK1 expression are correlated with poor prognostic outcomes in patients diagnosed with breast cancer." (PMID 39976088, 2025). "Cellular experiments revealed that overexpression of CDK1 substantially reversed the proliferation inhibition observed upon CD2BP2‐DT knockdown in breast cancer cells." (PMID 39976088, 2025). "A signature performed by four of these hub nodes (CDK1, PCNA, EZH2, and BUB1) was associated with relapse events in untreated luminal breast cancer patients." (PMID 38831458, 2024). "For example, circMETTL3 increase the expression of CDK1 by binding to miR-31-5p, thereby promoting the advancement of breast cancer." (PMID 39075555, 2024). "miR-489-3p has been found to increase the sensitivity of breast cancer cells via targeting cyclin-dependent kinase 1 (circCDK1)." (PMID 38339416, 2024). "Together, these results illustrate that D-arabinose has a pivotal role in modulation of cell cycle progression by regulating the activity of CDK1, Cyclin B1, p21, and p27 in breast cancer cells." (PMID 38789954, 2024). "In breast cancer, CDK1, CDK5, and CDK20 are overexpressed, while CDK2 and CDK6 are decreased, with high expression correlating with poor prognosis." (PMID 39567714, 2024). "It is proposed that CDK1 would be the best CDK target for breast cancer therapy since selective blockade of CDK1 alone or in combination with other therapies has been linked to strong anti-cancer results." (PMID 39567714, 2024). "CDK1 overexpression has been found in many cancers, including gastric cancer, ovarian cancer, oral squamous cell carcinoma, liver cancer, and breast cancer." (PMID 38605349, 2024). "PLD3 overexpression inhibited CDK1 activity by binding to and phosphorylating it, resulting in mitotic arrest and consequently, inhibiting breast cancer proliferation." (PMID 37978168, 2023). "CircCDK1 knockdown reduces CDK1 expression by targeting miR-489-3p to suppress the development of breast cancer and strengthen the sensitivity of tamoxifen." (PMID 37361693, 2023). "In vitro and in silico mode-of-action studies showed that pyranopyrazoles target CDK1 in human breast cancer cells, with lead compounds 5b and 5f having potent IC50 values of 960 nM and 7.16 μM, respectively." (PMID 36672680, 2023). "Since TWIST1 critically contributes to breast CSC‐like properties, we also evaluated the function of CDK1 in CSC properties of breast cancer cells." (PMID 36782089, 2023).
breast cancer (continued). "Our results demonstrated that nucleolar and spindle-associated protein 1 (NUSAP1), melatonin receptor 1A (MELT), and cyclin-dependent kinase 1 (CDK1) are three hub genes that play pivotal roles in the pathogenesis of breast cancer." (PMID 38084295, 2023). "PLD3 can bind with CDK1 and inhibit its expression, leading to mitotic arrest and inhibiting breast cancer proliferation." (PMID 37978168, 2023). "It serves as an oncogenic mediator in breast cancer by modulating CDK1 with a m6A‐independent manner." (PMID 37830241, 2023). "Inhibition of CDK1 suppressed the endometrial and breast cancer cell viability and colony-forming capacity." (PMID 37529110, 2023). "As a result of our report, we have provided new structures that can be used to develop molecules that target CDK1 in human breast cancer models." (PMID 36672680, 2023). "An expanding body of literature has provided compelling evidence linking elevated levels of CDK1 to the prognosis of various malignant tumors, encompassing lung cancer, breast cancer, pancreatic cancer, cervical cancer and colorectal cancer, ovarian cancer." (PMID 37986001, 2023). "This is in line with the study of Tan and colleagues which demonstrates that ERBB2 binds to and colocalizes with cyclin B-CDK1 complexes and phosphorylates Tyr15 of CDK1 in breast cancer cells." (PMID 37898722, 2023). "Recent reports have highlighted that high expression of Cdk1 is correlated with the growth of cancers and poor prognoses, such as epithelial ovarian cancer, breast cancer and lung cancer." (PMID 37047236, 2023). "Previous studies involving leukemia and breast cancer models have revealed that CDK1 relies more on CDK7-mediated activation activity and stability, while other CDK-activating kinases can also regulate CDK2, in addition to CDK7." (PMID 37507802, 2023). "CDK1 is a cell cycle-related protein that is considered a novel therapeutic target in breast cancer." (PMID 36699449, 2022). "In liver cancer, KIAA1429 regulated the expression of GATA3 in an m6A-dependent manner, while KIAA1429 played its oncogenic role in breast cancer by regulating CDK1 in an m6A-independent manner." (PMID 35217651, 2022). "While CDK 4/6 are the most studied members of the CDK family in relation to endocrine-resistant breast cancer, our analysis revealed another member of this family, CDK1 to be important for both endocrine resistance and TNBC." (PMID 35401937, 2022). "The writer KIAA1429 promotes proliferation and metastasis of breast cancer by modulating cyclin-dependent kinase 1 (CDK1)." (PMID 35721510, 2022). "CEP55 deletion can prime premature CDK1/cyclin B activation and mitotic cell death, thus sensitizing breast cancer cells to antimitotic drugs." (PMID 35681641, 2022). "This study concluded that d-limonene suppresses the proliferation of breast cancer cells by inducing G2/M phase arrest via deregulation of Cyclin B1/CDK1." (PMID 36307489, 2022). "The expression of circMETTL3 was also found to be increased in breast cancer, and promoted migration, proliferation and invasion of breast cancer cells by targeting miR-31-5p/CDK1." (PMID 35721510, 2022). "A study on breast cancer showed that KIAA1429 can be a carcinogenic factor of breast cancer by regulating CDK1 independently of m6A." (PMID 36389678, 2022). "For example, p62 depletion has been shown to induce cell cycle arrest by promoting cyclin-dependent kinase 1 (CDK1) degradation in human breast cancer." (PMID 35651787, 2022). "The results of the CPTAC database showed that the expression of total CDK1 protein in breast cancer, renal clear cell carcinoma, colon cancer, lung adenocarcinoma, and UCEC tissues was higher than that in the adjacent normal tissues (P < 0.0001)." (PMID 36090896, 2022). "The results showed that CDK1 was highly expressed in lung cancer tissues, liver cancer tissues, and breast cancer tissues, and the difference in expression between the cancer tissues and normal tissues was significant." (PMID 36090896, 2022).
breast cancer (continued). "CCNB1 and CDK1 were co-expressed in ACC, and this action was also acknowledged in breast cancer susceptibility, progression, and survival of Chinese women." (PMID 35983531, 2022). "Further, the significance of Cyclin B1 and CDK1 was highlighted for the first time in context to cell cycle arrest in d-limonene treated breast cancer cells." (PMID 36307489, 2022). "The total protein expression of CDK1 was significantly higher in some primary tumors, including breast cancer, colon cancer, lung cancer, KIRC, UCEC, LIHC, PAAD, GBM, and HNSC, as compared to normal tissues." (PMID 35681641, 2022). "In a breast cancer model, cannabinoids were able to induce cell cycle arrest via inhibition of cyclin dependent kinase 1 (CDK1), induction of p21 and p27, a decrease in cyclin A and E levels, degradation of CDC25A, and finally, inactivation of CDK2." (PMID 36291926, 2022). "Previous works also identified that a form of synthetic-lethal interaction between Myc overexpression and CDK1 inhibition in engineered breast cancer cell lines." (PMID 36005200, 2022). "In the past decade, a large body of literature has reported that CDK1 is highly expressed in hepatocellular carcinoma, lung cancer, breast cancer, thyroid cancer, colorectal cancer, prostate cancer and other malignant tumors." (PMID 35806389, 2022). "Immunohistochemistry staining also demonstrated a significant increase in CDK1 protein in breast cancer, colon cancer, and lung cancer tissues from patients but very minimal CDK1 protein in healthy human tissues." (PMID 35681641, 2022). "For example, blocking CDK1 expression combined with other therapies has shown strong anti-cancer effects for breast cancer patients." (PMID 35456460, 2022). "Using the area of the whole image for measurement, the mean optical density values of CDK1-positive expression in the corresponding cancer tissues of lung cancer, liver cancer, and breast cancer, as well as the normal tissues, were calculated." (PMID 36090896, 2022). "KIAA1429 increases the expression of cyclin-dependent kinase 1 (CDK1) mRNA to increase the invasion ability of breast cancer cells." (PMID 33643384, 2021). "Almost all SKP1 and CDK1 interactors were present in the breast cancer and Burkitt lymphoma networks." (PMID 33670716, 2021). "P21 is a mitotic regulator that can block the activation of CDK1 by binding with the CDK1/cyclinB1 complex and inhibiting the growth and proliferation of breast cancer cells in G2/M phase." (PMID 33718157, 2021). "Dysregulated CDK1 expression in breast cancer is closely related with tumor development, and CDK1 overexpression facilitates the growth, migration and invasion of cancer cells." (PMID 34585634, 2021). "The expression of CDK-1 was upregulated in 17 cancers including breast cancer, CRC, lung cancer and sarcoma in total unique analyses of 455 different datasets." (PMID 33732631, 2021). "Taken together, our results elucidate that circMETTL3 promotes breast cancer progression through circMETTL3/miR-31-5p/CDK1 axis." (PMID 33867838, 2021). "Cyclin-dependent kinase 1 (CDK1) in human breast cancer is degraded by p62- and HDAC6- mediated selective autophagy." (PMID 34777380, 2021). "Treatment of breast cancer cells with THC puts stress on the ER and downregulates cyclin-dependent kinase 1 (CDK1) and cell division cycle (Cdc2), causing arrested G2-M transition." (PMID 33802014, 2021). "The results show that after a 24 h treatment of NTX, PRO, and NTX + PRO, the levels of CDK1 and cyclin B were significantly downregulated in all three breast cancer cell lines." (PMID 34638341, 2021). "It has been shown that CDK1/2 targets are hyperphosphorylated in basal-like breast cancer, generating genome integrity vulnerability." (PMID 34646365, 2021).
breast cancer (continued). "In breast cancer, KIAA1429 also regulates downstream target genes such as CDK1, which encodes the protein cyclin-dependent kinase 1, a protein that exhibits a carcinogenic effect." (PMID 34422053, 2021). "VIRMA facilitated breast cancer by regulating the CDK1 mRNA expression in an m6A-independent manner." (PMID 33731118, 2021). "Poorly differentiated breast cancer tumors are characterized by specific set of over-expressed genes (e.g., UBE2C, CCNB2, CDK1, KIF2C, NDC80, and CCNB2) and are associated with more aggressive tumors and lower survival." (PMID 34300003, 2021). "Reverse experiments, RIP-seq, and RT-qPCR confirmed that CDK1 is the main target of VIRMA in breast cancer." (PMID 33731118, 2021). "For instance, FoxA1 interacts with the cyclin-dependent kinase 1 (Cdk1) cell cycle regulator in certain types of breast cancer cells." (PMID 34195082, 2021). "RBM7 promoted breast cancer cell proliferation by stabilizing CDK1 mRNA via binding to AREs in its 3'-UTR." (PMID 34804951, 2021). "KIAA1429 enhanced liver tumorigenesis through regulating GATA3 in a m6A-dependent manner and also act as an oncogene in breast cancer by modulating CDK1." (PMID 33748145, 2021). "The effects of alteration of the CDK1 gene are seen in many cancer types, including esophageal adenocarcinoma, breast cancer, oral squamous cell carcinoma, and hepatocellular and pancreatic adenocarcinoma." (PMID 34070979, 2021). "Some researchers have confirmed that KIAA1429 played its oncogenic role in breast cancer by regulating cyclin-dependent kinase 1 (CDK1)." (PMID 32258108, 2020). "Noticeably, PTTG1 gene, the transcriptional promoter of CDK1, was up-regulated in breast cancer; ZBTB16 gene was the transcriptional suppressor of CCNA2, and its expression was down-regulated in overlapping DEGs." (PMID 33083112, 2020). "Anti-differentiation non-coding RNA (lncRNA ANCR) suppresses breast cancer progression by promoting the cyclin dependent kinase 1 (CDK1)-mediated phosphorylation and degradation of EZH2." (PMID 32429086, 2020). "All the evidences implied RBM7 promoted breast cancer cell proliferation by stabilizing CDK1 mRNAs via binding to AREs in its 3′-UTR." (PMID 33145401, 2020). "Immunohistochemical analysis was used to measure CDK1 protein expression among 65 breast cancers and 13 normal breast tissues." (PMID 32424219, 2020). "BITC inhibited canine mammary tumor growth by suppressing cyclinB1 and Cdk1 expression in nude mice." (PMID 33263014, 2020). "And the ability of 5′-fluorouracil (5-FU) to reduce the expression of VIRMA and CDK1 has been certified, which offers a possible treatment for breast cancer." (PMID 32612834, 2020). "According to this research, the up-regulated VIRMA targets its downstream mRNAs like cyclin-dependent kinase 1 (CDK1) mRNA and enhances its translation in an m6A-dependent way to promote the progression of breast cancer." (PMID 32612834, 2020). "In this study, we identified 283 overlapping DEGs (105 up- and 178 down-regulated) and six hub genes (RRM2, CDC20, CCNB2, BUB1B, CDK1, CCNA2) associated with breast cancer tumorigenesis and progression based on multiple datasets." (PMID 33083112, 2020). "This indicated that RBM7 expression had a positive relationship with CDK1 expression in breast cancer tissues." (PMID 33145401, 2020). "CDK1 expression in breast cancer tissues are statistically significantly higher than those in the normal tissues (P < 0.002) with an AUC value of 0.71." (PMID 32424219, 2020). "The alteration of CDK1 has been found in numerous cancer types, including breast cancer, esophageal adenocarcinoma, hepatocellular carcinoma, pancreatic ductal adenocarcinoma, and oral squamous cell carcinoma." (PMID 32153633, 2020). "Both the cytoplasm and nucleus of ovarian and breast cancer cells can express CDK1, CHK2, PLK1, and Aurora A. CHK1 and pCDC25CSer216 were located only in the cytoplasm." (PMID 32393310, 2020).